PFKFB3 (6-phosphofructo-2-kinase/fructose-2,6-biphosphatase 3)
Diseases named in the same sentence as PFKFB3 in open-access papers (continued):
Sharing a sentence is not in itself a finding about the gene and the disease.
cancer (continued). "6-Phosphofructo-2-kinase/fructose-2,6-bisphosphatase isoform 3 (PFKFB3), a glycolytic enzyme highly expressed in cancer cells, has been reported to participate in regulating metabolism, angiogenesis, and autophagy." (PMID 31671668, 2019). "Distinct from the other three isoenzymes localized in cytoplasm, PFKFB3 is mainly localized in the nucleus of cancer cells." (PMID 31671668, 2019). "Our data showed that high PFKFB3/4 expression significantly correlates with shorter overall survival in several cancers." (PMID 31754349, 2019). "Regardless of the molecular mechanism of action of PFKFB3/4 isoenzymes our data clearly indicates that in analyzing the effect of PFK-II on the prognosis of cancer patients, the expression of both PFKFB3/4 isozymes should be considered." (PMID 31754349, 2019). "Consistent with its expression profile, the radiosensitizing effect upon PFKFB3 inhibition seems selective to cancer cells as survival of immortalized cells was only marginally affected at the doses affecting the survival of cancer cells upon IR." (PMID 30250201, 2018). "Consistent with PFKFB3 supporting cancer cell proliferation, PFKFB3 silencing on its own reduced clonogenic survival." (PMID 30250201, 2018). "Small-molecule inhibitors of PFKFB3, like 3-(3-pyridinyl)-1-(4-pyridinyl)-2-propen-1-one (3PO), have been reported to present a cytostatic effect on cancer cells." (PMID 29805774, 2018). "The PFKFB3 gene encodes the isoforms present in the brain, placenta and adipose tissue, and is the most expressed PFKFB gene in proliferating and cancer cells." (PMID 30234009, 2018). "Depletion of PFKFB3 by RNA interference in cancer cells delays cell cycle progression and inhibits anchorage-independent cell growth as well as reduces Ras-induced tumor growth in mice." (PMID 30250201, 2018). "Consistent with PFKFB3 being overexpressed in cancer, the viability of peripheral blood mononuclear cells (PBMCs) was not affected upon inhibition of PFKFB3 by KAN0438757." (PMID 30250201, 2018). "The inhibition of PFKFB3 has been shown to decrease glucose uptake and to promote autophagy in cancer cells." (PMID 30223793, 2018). "The glycolytic PFKFB3 enzyme is widely overexpressed in cancer cells and an emerging anti-cancer target." (PMID 30250201, 2018). "ROS-mediated S-glutathionylation or demethylation also regulate PFKFB3 in cancer cells, decreasing its catalytic activity and redirecting the glycolytic flux to the PPP, increasing NADPH and decreasing ROS levels." (PMID 30234009, 2018). "Pfkfb3 is overexpressed in many cancers, and it promotes cell proliferation through accelerating cell cycle progression and suppressing apoptosis." (PMID 30275866, 2018). "In this study, we demonstrate that PFKFB3 has a key role in protecting cancer cells from apoptosis induced by chemotherapy agent." (PMID 29410405, 2018). "Together, the roles of PFKFB3 on cancer cells are widely studied in cell lines and xenograft models." (PMID 29263928, 2017). "Elevated levels of PFKFB3 have been also reported in human embryonic kidney 293 cells and cancer stem (CS) cells." (PMID 29109698, 2017). "Given the critical role of PFKFB3 in glycolysis in most cancer cells by moderating the intercellular level of F26BP, we then verified the steady-state concentration of F26BP in HNSCC cells." (PMID 28061878, 2017). "Under different stimuli, the mechanisms involved in PFKFB3 regulation in different cancer cell lines differ." (PMID 29263928, 2017). "In conclusion, recent studies have provided a new insight into the mechanism of PFKFB3-regulated cell proliferation and develop more promising anti-cancer therapy strategy." (PMID 28977989, 2017). "6-Phosphofructo-2-kinase/fructose-2,6-bisphosphatase isoform 3 (PFKFB3), is a critical enzyme for glycolysis and highly expressed in cancer cells." (PMID 29113354, 2017).
cancer (continued). "Most studies have demonstrated that cancer cell growth, proliferation, migration and metastasis are promoted when PFKFB3 expression is increased or the PFKFB3 isoenzyme is phosphorylated." (PMID 29263928, 2017). "Similar findings have been reported in cancer cells and M1 macrophages, highlighting a potentially conserved critical role for PFKFB3 in aerobic glycolysis." (PMID 29109698, 2017). "Given that this gene is commonly overexpressed in human cancers, including breast, colon, ovarian and thyroid carcinomas, but is insufficiently expressed in normal tissues, targeting PFKFB3 presents a promising strategy for cancer treatment." (PMID 28061878, 2017). "In this review, we summarize current knowledge of PFKFB3 regulation by several signal pathways and its function in cancer development in different cell types in cancer tissues." (PMID 29263928, 2017). "Meanwhile, a new class of 3PO derivatives has been synthesized in an attempt to improve the pharmacokinetic properties and toxicological parameters of the drug candidate in a study focusing on the inhibition of PFKFB3-driven glycolysis in cancer cells." (PMID 29263247, 2017). "Although the glycolytic role of PFKFB3 in cancer progression has been the subject of numerous functional studies, some researchers have also focused on the functions of PFKFB3 beyond glycolysis." (PMID 29263928, 2017). "Most of the PFKFB3 positive staining was observed in the nuclei of the carcinoma cells, and cytoplasmic positive signals were detected in a much weaker level." (PMID 28061878, 2017). "PFKFB3 is a master regulator of glycolysis, whose increase contributes to cancer cell growth and survivals." (PMID 27079271, 2016). "Compared with those in normal epithelium, the mRNA levels of PFKFB3 were increased in both cancer tissues and its surrounding tissues, which were accompanied with significant decreases in the mRNA levels of BMAL1 and CLOCK in the same tissues." (PMID 27079271, 2016). "The pertinent results support a role for PFKFB3 in the control of cancer growth by responding to circadian clock outputs." (PMID 27079271, 2016). "In summary, the present study provides compelling evidence, for the first time, to support a link between circadian clock dysregulation and increased PFKFB3 expression in the context of cancer bio-physiology." (PMID 27079271, 2016). "PFK15 has been reported to be a specific and potent small molecule antagonist of PFKFB3, and is able to suppress the proliferation of various cancer cells at relatively low concentrations." (PMID 27669567, 2016). "Taken together, these findings demonstrate PFKFB3 as a mediator of circadian control of cancer growth, thereby highlighting the importance of time-based PFKFB3 inhibition in cancer treatment." (PMID 27079271, 2016). "PFKFB3 is a key regulator of high glycolytic flux in cancers by catalyzing the synthesis of F2,6P2 which allosterically activates PFK-1, the rate-limiting enzyme of glycolysis." (PMID 27669567, 2016). "In other words, PFKFB3 appears to serve as a mediator that links circadian clocks and the growth of cancer cells." (PMID 27079271, 2016). "As suggested by the results from cancer cells upon timed PFKFB3 inhibition, it is very likely that 3PO directly inhibited the PFKFB3 of implanted cancer cells at CT7, thereby increasing apoptosis of the implanted cancer cells." (PMID 27079271, 2016). "Taken together, these results suggest that timed PFKFB3 inhibition generates different outcomes on cancer growth, which is attributable to differential effects of timed PFKFB3 inhibition on cancer cell proliferation and apoptosis." (PMID 27079271, 2016). "In combination, these results suggest that PFKFB3 inhibition at its peak expression time generates better efficacy at inhibiting proliferation and stimulating apoptosis of cancer cells." (PMID 27079271, 2016).
cancer (continued). "Based on this link, the effects of timed PFKFB3 inhibition were examined in cultured cancer cells and in mice implanted with cancer cells." (PMID 27079271, 2016). "This, in turn, led to improved efficacy of PFKFB3 inhibition at reducing the proliferation of cancer cells, which appeared to be due to improved efficacy at reducing the expression of anti-apoptotic genes and at increasing the expression of apoptotic enzymes." (PMID 27079271, 2016). "Gene expression analysis showed that the PFKFB3 mRNA level is several fold higher in cancer, CSC and iPS cells cultured in hypoxic conditions compared to normoxic conditions." (PMID 26337471, 2015). "In our study, both pharmacological and genetic knockdown of PFKFB3 expression influenced the glycolytic activity in cancer cells and iPS cells." (PMID 26337471, 2015). "As PFKFB3 plays an important role in glycolysis, we examined the effect of inhibiting glycolysis on PFKFB3 expression and ATP level in cancer-, iPS cells, and fibroblasts." (PMID 26337471, 2015). "Our data demonstrate also that the exposure of cancer cells to hypoxia changed the expression of PFKFB3 and PFK1 to levels resembling those in CSCs." (PMID 26337471, 2015). "Our results showed that hypoxia increased the expression of PFKFB3 in cancer and iPS cells, which is in agreement with other reports." (PMID 26337471, 2015). "PFKFB3 possess a hypoxia-responsive element, which leads to induction of PFKFB3 in various cancer cell lines." (PMID 26337471, 2015). "Western blot analysis showed that PFKFB3 is undetectable in iPS cells and human primary fibroblasts when compared with cancer and CSC." (PMID 26337471, 2015). "In comparison to the Western blot analysis, significantly higher expression of PFKFB3 mRNA was observed in CSC than in differentiated cancer cells." (PMID 26337471, 2015). "Our results provide a new insight into the molecular mechanism of PFKFB3-regulated cell cycle progression and arouse hope for developing more effective anti-cancer therapies." (PMID 26337471, 2015). "Previous studies have shown that the ubiquitous isoform of PFK2/FBPase2 (PFKFB3) localises to the nuclear compartment of cancer cells but the location of the liver isoform of PFK2/FBPase2 (PFKFB1) has not been investigated." (PMID 24566088, 2014). "One family member, PFKFB3, has been shown to be highly expressed and activated in human cancer cells, and derivatives of a PFKFB3 inhibitor, 3-(3-pyridinyl)-1-(4-pyridinyl)-2-propen-1-one (3PO), are currently being developed in clinical trials." (PMID 24451478, 2014). "Although the precise mechanisms for high PFKFB3 expression in human cancers are not fully understood, PFKFB3 mRNA transcription is promoted by HIF-1α and by the progesterone receptor." (PMID 24451478, 2014). "This study validates PFKFB3 as a target for new cancer therapies and provides a framework for future development efforts." (PMID 21957443, 2011). "Similar to cancer cells, M1 macrophages upregulate PFKFB3 to boost the rate of glycolysis." (PMID 41235226, 2025). "Additionally, it was demonstrated that endothelial PFKFB3 and lactate enhanced polarization of M2-like macrophages in a murine ischemia model, suggesting a potential role in modulating immune responses in cancer as well." (PMID 41235226, 2025). "Recently, Zhang and colleagues demonstrated that the overexpression of miR-519d-3p significantly reduced CRC cell proliferation, enhanced apoptosis, and increased sensitivity to 5-Fu, suppressing PFKFB3, a key glycolytic enzyme involved in cancer cell metabolism and chemoresistance." (PMID 40871106, 2025). "Furthermore, modulation of the glycolytic pathway by 3PO induces apoptosis in cancer cells, which supports PFKFB3’s role in cell survival and stress adaptation." (PMID 40600018, 2025). "Thus, PFKFB3 inhibition has been considered as a compelling therapeutic strategy in glucose-dependent cancers." (PMID 40612109, 2025).
cancer (continued). "PFKFB3 inhibitor has been reported to inhibit the progression of several types of cancer." (PMID 41292194, 2025). "These contradictory findings stress the need for more research to explore how PFKFB3 inhibition may affect the cancer-immune interaction." (PMID 41235226, 2025). "PFKFB3 is a metabolic enzyme and a suggested cancer treatment target." (PMID 40022029, 2025). "PFKFB3 is a bifunctional enzyme that is indispensable for cell cycle progression (such as glycolysis, cell proliferation, and adhesion) and the prevention of apoptosis, which makes it as a promising novel target for the therapeutic arsenal against cancer." (PMID 40487778, 2025). "Similarly, nuclear 6-Phosphofructo-2-Kinase/Fructose-2,6-Biphosphatase 3 (PFKFB3) can enhance HR repair in cancer cells by modulating cellular deoxyribonucleotide triphosphate (dNTP) levels." (PMID 40261702, 2025). "In addition, inhibition of PFKFB3 was found to be associated with decreased insulin-stimulated glucose uptake, GLUT4 translocation, AKT signaling, and glycolytic flux in cancer cells and adipocytes." (PMID 38510704, 2024). "Furthermore, PFKFB3 regulates cancer stemness in small cell lung cancer via the Hippo pathway, and its inhibition affects cancer stemness markers like CD44, associated with chemotherapy resistance." (PMID 39010066, 2024). "During the past several years, the function of PFKFB3 in cancer has advanced considerably." (PMID 38622715, 2024). "AGPG binds to and stabilizes 6‐phosphofructo‐2‐kinase/fructose‐2,6‐biphosphatase 3 (PFKFB3), protecting it from proteasomal degradation, leading to the accumulation of PFKFB3 in cancer cells, which subsequently activates glycolytic flux and promotes cell cycle progression." (PMID 37042179, 2023). "However, pan-cancer evidence has yet to be established to interpret the function of PFKFB3 in TME and the clinical prognosis of different cancers." (PMID 37253634, 2023). "Therefore, PFKFB3 has attracted much attention and is regarded as a promising target for cancer therapy, and many novel compounds have been reported with potent PFKFB3 inhibitory activities." (PMID 37035116, 2023). "Herein, a strategy is presented where glycolysis is inhibited in cancer cells using PFK15 (inhibitor of PFKFB3, rate-limiting step in glycolysis), while simultaneously glycolysis and function is rescued in DCs by delivery of fructose-1,6-biphosphate (F16BP, one-step downstream of PFKFB3)." (PMID 37660049, 2023). "In addition, PFKFB3 showed the most potent activity compared with the other 3 isozymes, making it a driving force of cancer oxygen-independent glycolysis." (PMID 37035116, 2023). "Moreover, it has been shown that PFKFB3 is an important target in the glycolytic pathway for retarding cancer cell growth." (PMID 37660049, 2023). "Finally, single-cell analysis has shown the characteristic of the expression of PFKFB3 on different types of immune cells of TME in pan-cancer." (PMID 37253634, 2023). "lncRNAs promote energy metabolism and cancer progression through posttranslational modifications of key metabolite‐related proteins, and they can activate glycolytic flux by binding 6‐phosphofructo‐2‐kinase/PFK2/fructose 2,6‐bisphosphatase (PFKFB3)." (PMID 36994237, 2023). "Genes related to rs117719091 (PFKFB3) and rs140233124 (KIAA0232) play crucial roles in cancer metabolism; PFKFB3 induces glycolysis and activates hepatic stellate cells and then promotes liver fibrosis, and KIAA0232 stimulates insulin secretion to regulate cancer metabolism." (PMID 38003606, 2023). "Indeed, there is one report (in need of further confirmation) of secretion of PFKFB3 by cancer cells with consequent effects on endothelial cell proliferation in a nasopharyngeal cancer setting." (PMID 37561190, 2023). "Recent investigations address the glycolytic roles of PFKFB3 in cancer." (PMID 36984785, 2023).
cancer (continued). "Therefore, when CDH1 is depleted, increased PFKFB3 causes an upregulation of glycolysis and cell proliferation, suggesting that APC/CCDH1 modulation is important in cancer metabolism alteration." (PMID 37176148, 2023). "PFKFB3 is upregulated in cancer and its overexpression correlates with poor patient outcome in BC." (PMID 37561190, 2023). "Besides, we further analyzed the distribution of the PFKFB3 expression in different TME cells in pan-cancer." (PMID 37253634, 2023). "Therefore, CO- dependent regulation of PFKFB3 methylation regulates glucose consumption to confirm resistance against oxidative stress for cancer cell survival." (PMID 36978983, 2023). "Finally, molecular docking was used to predict the anti-cancer activity of the compound against PFKFB3 kinase and presented noticeable hydrophilic and hydrophobic interactions at the active site region." (PMID 37920528, 2023). "In several types of cancer, including breast, colon, and lung cancer, PFKFB3 is overexpressed, and it leads to an increase in the levels of fructose-2,6-bisphosphate, an enzyme that promotes cell proliferation and survival, and thus contributes to cancer cell growth and proliferation." (PMID 37176148, 2023). "This might be indicative of a systemic reduction in mitochondrial activity in carcinoma patients, consistent with the potential loss of PGC-1α activation capacity and altered PRDX3/PFKFB3 correlation." (PMID 37047426, 2023). "In number of cancers, PFKFB3 expression was increased compared to normal tissue." (PMID 36733385, 2022). "All such findings render PFKFB3 an important drug-target molecule in other cancer models." (PMID 35057732, 2022). "Pfkfb3 mRNA contains a destabilising ARE61 that is bound by ZFP36 in human cancer cells." (PMID 36385275, 2022). "We found that targeting PFKFB3 offered a promising therapeutic approach for cancer therapeutics." (PMID 35804016, 2022). "Moreover, 6-phosphofructo-2-kinase/fructose-2,6-biphosphatase 3 (PFKFB3) was reported to be a critical downstream target of activated AMPK to induce glycolysis in cancer cells, including A549 cells." (PMID 35681729, 2022). "However, the therapeutic efficacy of PFKFB3 inhibition targeting cancer stemness remain unidentified." (PMID 35804016, 2022). "Increased expression of PFKFB3 in several cancers and inflammatory diseases has been previously reported, but the metabolic status of fibroblasts and the role of PFKFB3 in patients with IBD are currently unknown." (PMID 36405760, 2022). "tRiMetF31 was downregulated, whereas PFKFB3 was overexpressed in cancer cell lines." (PMID 35961977, 2022). "Compared with that in monolayer or ALDH-CD44- cancer cells, significantly higher PFKFB3 mRNA expression was clearly detected in tumorspheres derived from ascites and ascites-derived cell lines (SKOV3 and OVCAR3) or ALDH+CD44+ cells sorted from SKOV3 and OVCAR3 cells." (PMID 35155224, 2022). "Therefore, the PFKFB3 controls glycolytic level in cells, as its expression involves in dysregulated growth of many cancer cells." (PMID 36077431, 2022). "Furthermore, tumorspheres and the ALDH+CD44+ cell subset originating from ascites had greater expression of PFKFB3 than differentiated cancer cells." (PMID 35155224, 2022). "PFKFB3 expression is reported to be significantly higher in many cancers." (PMID 35804016, 2022). "It has also been found that PFKFB3 promotes the interleukin-8 coding gene CXCL8 by activating the PI3K/AKT/NFκB p65 pathway, which leads to the idea that PFKFB3 inhibition might be effective in overcoming trastuzumab resistance in HER2-positive cancers." (PMID 36143438, 2022). "Further, to understand the role of YAP/TAZ in PFKFB3 mediated regression of cancer stemness and ABCG2 expression, XMU-MP-1 (an inhibitor that activates YAP/TAZ via MST1/2 inhibition) used to activate YAP/TAZ in H1048CSC and H1882CSC cells and when treated with PFK158." (PMID 35804016, 2022).